IL1B (interleukin 1 beta)
Diseases named in the same sentence as IL1B in open-access papers (continued):
Sharing a sentence is not in itself a finding about the gene and the disease.
infection (continued). "Analysis of inflammatory markers revealed that, starting at 6 h post-infection, E. coli-Tb strains capable of secreting Ybt induced significantly higher levels of IL-1β in cells compared to strains lacking Ybt (TbΔirp2)." (PMID 40034497, 2025). "Lastly, exclusive expression of many genes encoding immune mediators, which allocate to signaling by interleukins or chemokines could be detected in male-derived macrophages upon infection at 6 hpi, such as CXCL1, IL32, CCL7 and IL1B." (PMID 40794782, 2025). "The study also suggests a role for fetal infection in regulating the activity of the NLRP3 inflammasome in utero and the important developmental mechanisms regulating IL-1β responses early in gestation, in part due to a downregulation of TLR-mediated NLRP3 expression." (PMID 41149694, 2025). "Notably, the intensity of GSDME, GSDMD, caspase-3, and caspase-1 cleavage was strikingly more pronounced over the time course of Brazil/78 infection, correlating with significantly greater IL-1β and LDH release at 18 and 24 h post-infection." (PMID 40481027, 2025). "PTX3 is produced locally at the site of infection and inflammation by a variety of cell types including fibroblasts, endothelial cells, mononuclear phagocytes, and DCs in response to pro-inflammatory signals such as TNF-α, IL-1β, Toll-like receptor agonist." (PMID 40646589, 2025). "CF airway epithelial cells demonstrated significantly higher levels of released IL-8 and IL-6 in response to IL-1β stimulation, in the absence of any infection or microbial stimuli in vitro." (PMID 40791588, 2025). "In the brain, infection with Bov342 induced the expression of type-I (Ifna5, Ifnb), -II (Ifng), and -III (Ifnl2) interferons (IFN), interferon stimulated genes (ISGs) (Isg15, Ifit1, Mx1, Oas1), and pro-inflammatory cytokines (Il1b, Il6, and Tnfa) at endpoint." (PMID 40410375, 2025). "Lastly, IL-1β release temporally mirrored LDH release following both Brazil/78 and HKx31 infection." (PMID 40481027, 2025). "IL-1β is mainly released by monocytes, macrophages and non-immune cells during cell injury and infection, which can promote the production of other cytokines and play an important role in immune response." (PMID 40867713, 2025). "We found that 1,25(OH)2D3 upregulated IL-1β gene expression in the absence of infection and in the presence of T. forsythia, but not at the protein level." (PMID 40725246, 2025). "At 6 dpi, the presence of copper during the assay resulted in a significant reduction in IL-1β mRNA and proinflammatory cytokines (TNF-α and IL-12) produced in response to MtbΔctpA infection, as compared to the levels observed at the same period of infection in the absence of the metal." (PMID 40002852, 2025). "To further examine B cells as a source of IL-1β in vivo, we examined naïve B cells (CD19 + IgD+), activated but non-GC (nGC) B cells (CD19 + IgD-GL7-CD95-), and GC B cells (CD19 + IgD-GL7 + CD95+) post A/PR8 infection." (PMID 40825032, 2025). "In PwCF, IL-1β was detected in the bronchoalveolar lavage fluid even without infection, its airway levels increased in the presence of bacterial infection and correlated with the neutrophil count and NE activity in CF airways." (PMID 40791588, 2025). "It is interesting that the pulmonary IL-6 level, but not the IL-1β or TNFα levels, significantly decreased in mice deficient in caspase-11 or NLRP3 upon infection." (PMID 40034692, 2025). "This was significantly increased with the addition of exogenous IL-1β at concentrations observed during infection, which had no impact in the absence of SpeA." (PMID 39878494, 2025). "In the infection of human monocytic cell line THP-1 cells with the N. caninum dense granule protein 7 knock-out (NcGRA7KO) parasite and the parental strain Nc1, production of IL-1β and TNF-α, phosphorylated NF-κB p65 were measured." (PMID 41357231, 2025).
infection (continued). "Consistent with the lack of effect on BR15 infection, AbII treatment did not significantly alter the levels of IL-1β, IL-6, IL-10, CCL2 (MCP-1), CCL5 (RANTES), or CXCL8 (IL-8) in BR15-infected cells." (PMID 40732762, 2025). "Stimulation of both primary monocytes and THP-1 reporter cell lines with SARS-CoV-2-derived ssRNA led to profound upregulation of all measured cytokine genes, while primary monocytes increased TNF, IL1B and IL6 and decreased CXCL8 expression upon infection with replication-competent SARS-CoV-2." (PMID 39963132, 2025). "These included interferons (IFN-α, IFN-β, and IFN-γ), proinflammatory factors (IL-1β, IL-6, and TNF-α), the anti-inflammatory cytokine (IL-10), and matrix metalloproteinases 3 (which contribute to blood-brain barrier disruption) after TMUV infection." (PMID 40401981, 2025). "At 48 h post-infection, the supernatant of U937 macrophages infected with LRV-1+ isolates contained significantly higher concentrations of TNF-α (p < 0.01) and IL-1β (p < 0.0001), but a lower concentration of IFN-γ (p < 0.01), compared to macrophages infected with LRV-1− isolates." (PMID 41471220, 2025). "Native promoter regulation of ACE2 expression in macrophages appears dynamic and based upon IL-1β-driven NF-κB transcription of ACE2, and this mechanism may be potentially targeted to influence the macrophage response to infection." (PMID 39763770, 2025). "To determine the mRNA expression levels of IFN-γ, TNF-α, IL-1β, and IL-18, as well as the abundance of cytokines IFN-γ, TNF-α, IL-6, and IL-10 in the kidneys of uninfected and PbA-infected mice at day 7 post-infection, we performed quantitative real-time PCR and CBA assays, respectively." (PMID 38787228, 2024). "IL-1β and IL-18 levels were reduced in the lungs of Gsdmd−/− mice after infection but levels of these cytokines were not entirely dependent on GSDMD, despite the canonical role of GSDMD in IL-1β and IL-18 release." (PMID 38553499, 2024). "This is not the first report of IL-1α and IL-1β seemingly having differential roles during infection." (PMID 39127259, 2024). "Elevated levels of the cytokines IL-1β (32.23±12.58 pg/ml) and IL-6 (45.12±16.03 pg/ml) were detected in the cerebrospinal fluid of these patients without any signs of infection." (PMID 39006838, 2024). "This post-infection reduction in levels of Clostridia were not dependent on preinfection conditions as co-housing and streptomycin treatment of WT and IL-1β-/- mice did not result in differences in Clostridia levels." (PMID 38236896, 2024). "IL-1β exhibited a similar pattern, with elevated levels in the death group throughout the infection, though these levels remained stable without a clear trend of increase or decrease." (PMID 39408907, 2024). "In addition, quercetin can inhibit the exaggerated inflammatory response following infection via subsiding the expression of TNF-α, IL-1β, and IL-6 in macrophages." (PMID 39575436, 2024). "A detailed analysis of the data for active (M2) or chronic (M4.M4.1) DD lesions suggests that the SCFP group exhibits a more rapid IL-1β response to infection with Gram-negative bacteria, as simulated by LPS stimulation." (PMID 39595313, 2024). "In previous studies, some anti-inflammatory drugs, such as canakinumab (a fully human monoclonal antibody targeting the IL-1β) and methotrexate (a systemic anti- inflammatory drug targeting TNF-α), were limited in clinical practice by frequent infection events." (PMID 38988665, 2024). "In addition, 25–100 mg/kg baicalin attenuated the changes in IL-1β, IL-10, IL-18, TNF-α and IFN-γ mRNA expression compared to that in the infection group (P < 0.01)." (PMID 39075562, 2024). "In contrast with IL-4, IL-5, and IL-13, mRNA expression of IL-1β and TNF-α, both considered type 1 cytokines, decreased after infection with RV2, suggesting that RV infection on day 6 of life skewed the response to subsequent heterologous RV infection toward a type 2 phenotype." (PMID 38061015, 2024).
infection (continued). "IL-1β promotes the production of other proinflammatory cytokines, such as TNF-α and IL-6, and induces the expression of adhesion molecules and chemokines, which attract immune cells to the site of injury or infection." (PMID 38397895, 2024). "However, infection with the ΔprrH/Vector, ΔexsA/Vector, and the ΔexsA/PrrH strains suppressed the expression of TNF-α and IL-1β." (PMID 38289930, 2024). "Specifically, using mouse macrophage-like J774A.1 cells in an in vitro biofilm infection model, it became evident that S. epidermidis 1457 is a less potent activator of NF-κB and Il-1β production compared to biofilm-negative mutant 1457-M1036." (PMID 39567551, 2024). "In addition, infection with different doses of PEDV led to a dose-dependent increasing trend in IL-1β mRNA expression, while the IL-1β secretion in the cell supernatants also increased in a dose-dependent manner, according to the ELISA results." (PMID 39728983, 2024). "This resistance of IL-1β-/- mice was also present in co-housed WT and IL-1β-/- mice, indicating that microbiota differences before infection did not affect mortality in these experiments." (PMID 38236896, 2024). "After infection of CIECs with 106 CFU/ml C. jejuni 11168, Lior6 or 0097, the expression patterns of the interleukin (IL)-1β and IL-6 mRNAs, which are proinflammatory cytokines known to be upregulated after C. jejuni infection of chickens, were investigated via qRT‒PCR." (PMID 38907359, 2024). "Neutrophil-derived IL-1β had no impact on the number of CFUs after infection with BCG, H37Rv, or HN878 at the time point examined." (PMID 38803236, 2024). "Moreover, infection may also trigger the differentiation of naive T cells into T helper 17 (Th17) cells and the release of IL-17, which is a strong inducer of tissue neutrophilia, via the upregulation of the production of pro-inflammatory cytokines such as TNFα and IL-1β from macrophages." (PMID 38791316, 2024). "In contrast, no statistically significant result was found when the IL-1β mRNA levels of the healthy control group and the post-infection day 10 group were compared (p > 0.05)." (PMID 39766497, 2024). "Therefore, we quantified TNF-α, IL-1β, and IL-6 cytokine levels in PAM culture supernatants that were collected at 24- and 48-h post-infection using commercially available ELISA kits." (PMID 38664855, 2024). "Keratinocytes also produce a differentiating IL-1β response, which fits well with previous work in mouse models which demonstrated that IL-1β was generated by S. aureus intradermal infection but not epicutanous." (PMID 39208402, 2024). "And found the expression of IL-1β in the ileum was elevated after 24 hours post-infection, whereas there was no significant change in the IL-23 level." (PMID 39435479, 2024). "Furthermore, large cohort studies have revealed elevated levels of IL-1β, IL-6, and TNF in the serum of clinical patients with an average period of 8 months after infection." (PMID 38299028, 2024). "Indeed, compared to HC and IPF patients (which again overall behaved similarly), M-COV1/2 PBMCs secreted, upon infection with live PAO1, less IL-8, MIP-1α, IL-1α, IL-1b, TNF-α, G-CSF, MIP-2α, IL-23 and IL-10." (PMID 38835759, 2024). "The qRT-PCR results showed a peak in IL-1β transcript for M. bovis SB1564 strain, as observed with the ELISA test, and MAP while it appeared reduced with M. bovis SB0841 and absent in the mixed infection with eventually a peak at one-week post-infection." (PMID 38399810, 2024). "After infection with Streptococcus pneumoniae (S. pneumoniae), ATF3 regulates GPB5 or forms a complex with JUN, thus promoting the production of inflammatory cytokines (TNF-α, IL-1β, IL-6, and IFN-γ)." (PMID 38255898, 2024). "Therefore, we examined the expression of cytokine genes (IL-1β, IL-6, IL-10, TNF-α, and GM-CSF) after infection." (PMID 38903792, 2024).
infection (continued). "To determine whether sPro-IL-1β was cleaved during infection, we challenged HEK-293T cells stably expressing sPro-IL-1β with SVV (MOI = 0.1, 0.5, 1, and 5), and collected the cells at 16 h post-infection." (PMID 39038050, 2024). "When the piglets were injected with baicalin and probenecid, the IL-1β, IL-10, IL-18, TNF-α and IFN-γ mRNA levels decreased compared to those in the infection group (p < 0.01), which suggested that baicalin and probenecid inhibited cytokine production in piglets infected with G. parasuis." (PMID 39075542, 2024). "Additionally, there was a significant increase in IL-1β, IL-6, and TNF-α levels in response to CR-hvKP57 infection, indicating varying degrees of inflammatory response." (PMID 39211794, 2024). "The data suggest a dual role for ISG15 in modulating the immune landscape in DM, in terms of M1 macrophages, when the infection or inflammation is severe enough to affect an organ, macrophages first exhibit the M1 phenotype to release TNF-α, IL-1β, IL-12, and IL-23 against the stimulus." (PMID 39559355, 2024). "p. i, but it induced lower levels of IL-1β, IL-18, and GSDMD-NT, which led to an alleviated inflammatory infiltration and pathological damage in the lungs and brains, and a lower death rate compared with wild-type PRV strain infection." (PMID 39316625, 2024). "In the present study, we found that infection with GoAstV activated the NLRP3 pathway, and the mRNA expression levels of NLRP3, cleaved caspase-1 and IL-1β were significantly upregulated in the infection group at 24 hpi and 48 hpi compared to those in the control group." (PMID 39502173, 2024). "The results demonstrated that, influenced by the liver parasitic infection, pro-inflammatory factors IL-1β and TNF-α exhibited continuous increases in both serum and liver levels at all infection stages, while anti-inflammatory factors IL-4 and IL-10 showed persistent decreases." (PMID 39749332, 2024). "The expression of IL-1β, however, was not reduced in mice rescued from infection with anti-CD8 mAb, suggesting that this nominally pro-inflammatory cytokine does not contribute to lethal pathology." (PMID 38543756, 2024). "Among patients without a post-operative infection, there was an increase in monocyte IL-1β (p = 0.0141) and a reduction in CXCR4 (p = 0.004) in pre-operative samples." (PMID 38655251, 2024). "Using small molecule inhibitors designed to inhibit Mip, we demonstrated that treatment of B. pseudomallei-infected murine macrophages with the inhibitor AN_CH_37 resulted in a decrease in secreted pro-inflammatory cytokines IL-1β, TNFα and IL-6, and an increase in MCP-1, 24 hours post-infection." (PMID 38590438, 2024). "In addition, after 7 days of infection with the wild-type strain, the concentrations of the inflammation cytokines TNF-α and IL-1β in the brain tissue of mice showed a significant increase." (PMID 39240104, 2024). "During infection, proinflammatory Ly6Chi monocytes are recruited into the site of inflammation, where they differentiate into inflammatory macrophages that produce high levels of inflammatory cytokines such as IL-6, TNF-α, IL-1β." (PMID 38646937, 2024). "This enables neutrophils to support IL-1β production at the infection site without compromising their essential antimicrobial function, which would be lost if they rapidly underwent cellular lysis after Caspase-1 activation." (PMID 38294676, 2024). "In KO THP-1dM cells, production of active caspase-1 was significantly reduced by Lt-P10 infection (p = 0.004), whereas IL-1β production was increased, although not significantly." (PMID 38707903, 2024). "Despite bacterial clearance not being affected by glutamine, IL-1β secretion was dampened in the absence of glutamine 72 hours after infection." (PMID 39605528, 2024).
infection (continued). "(B.2.1) Endothelial cells stimulated by IL-37 expression through the secretion of inflammatory mediators, including IL-1β, TNF-α, and IFN-γ, which positively induce adhesion molecules like E-selectin, ICAM-1, VCAM- 1, and VLA-4 that allow immune cells to go to the infection site." (PMID 39308868, 2024). "Matching the data collected during the physical characterization of the NTHi-NHNE infection, expression levels of key chemo- and cytokines (e.g. CXCL8, IL-6, IL-1β, CCL3, CXCL1 & CXCL2) and genes involved in ECM remodelling and inflammation (PLAU, Serpine1, MMP9) increased further on day14." (PMID 38990812, 2024). "It has been observed that while M. gallisepticum infection alone upregulates pro-inflammatory factors such as TNF-α, IL-1β and IL-6, the presence of M. gallisepticum-derived EVs results in a dose-dependent suppression of these factors in HD11 cells at 24 h post-infection." (PMID 38474071, 2024). "A significant difference in IL-1β was observed at 30 days post-infection, but there was no change at 90 days post-infection compared to Ms_Vc." (PMID 38803374, 2024). "While a transient reduction in IL-1β, IL-6 and tumour necrosis factor (TNF) secretion was observed during acute infection, levels returned back to WT or higher 5 days post-infection (dpi), suggesting ablation of AIM2 may rather facilitate severe inflammation." (PMID 39459869, 2024). "Moreover, we probed for the expression of proinflammatory cytokines mRNA, including Tnf, Il1b, and Il6, and found that their levels were significantly higher in the lungs of PM2.5-exposed mice upon infection." (PMID 38355515, 2024). "Compared to infection with untreated control and DNAseI-treated cultures of S. epidermidis 1457-M10, exogenously added chromosomal DNA had no significant impact on hMDM IL1B or IL10 expression." (PMID 39567551, 2024). "Three genes were not deregulated after infection with any of the viruses tested: sacs, il-1β and granb." (PMID 38921776, 2024). "In contrast, and in line with observations made using ODN TAAGGG to inhibit TLR9 activation in hMDM, infection of murine wild-type macrophages with S. epidermidis 1457 did not induce IL1b compared to the untreated control." (PMID 39567551, 2024). "Measurement of chemokines in the lung showed several alterations in global IFNLR1-/- mice compared to WT mice both during super-infection and single S. aureus infection, including increased TNFα, CXCL11, CXCL12, and MIP3α and decreased IL-1β, MIP1β, and CXCL16." (PMID 39178311, 2024). "Additionally, infection with Herpes simplex virus (HSV) also instigates the creation of NLRP3 inflammasomes and consequent IL-1β production in human TH-1 cells, fibroblasts, and melanoma cells." (PMID 38590522, 2024). "MCC950 did not lead to a complete block of IL-1β production during infection, thereby maintaining the anti-infection response." (PMID 38957662, 2024). "For example, during early infection of P. falciparum, the infected RBC-derived PFHRPII interacted with BMECs, activating endothelial NFκB signaling, leading to the release of inflammatory mediators such as IL-6 IL-1B CCL5 and IFNβ1." (PMID 38360663, 2024). "Though not historically considered major cytokine producers, neutrophils do also produce a range of cytokines and chemokines, such as TNF, IL-1β, IFNγ, IL-4, IL-10, IL-13, IL-17, CXCL8, and CXCL9/10, which contribute to shaping the inflammatory response to infection." (PMID 39015565, 2024). "Interestingly, g2g-L2 strain infection dampened the IFN response in all donors, instead promoting an IL-1B-dominated response." (PMID 39613754, 2024). "Infection with ZIKV including MR766 induces inflammatory cytokines such as TNF-α, IL-6 and IL-1β." (PMID 39178324, 2024).